SCDP1 (stearoyl-CoA desaturase pseudogene 1)
Synonyms: formerly SCDP
Gene: Processed pseudogene on chromosome 17 (20,784,645 to 20,785,725, forward strand). Ensembl gene ENSG00000226549.
Diseases named in the same sentence as SCDP1 in open-access papers:
SCDP1 is named in the same sentence as 2 diseases in open-access papers, as found by Europe PMC text mining. Sharing a sentence is not in itself a finding about the gene and the disease.
SCDP1 shares sentences with these, for which no sentence is quoted: tumor (2 papers); hepatoma (1).